ALB (albumin)
Diseases named in the same sentence as ALB in open-access papers (continued):
Sharing a sentence is not in itself a finding about the gene and the disease.
Hypoalbuminemia (continued). "As earlier reiterated, this study aimed to determine the association between hypoalbuminemia, reversal of albumin-to-globulin ratio and morbidity outcome among confirmed LF-infected patients." (PMID 33312698, 2020). "Serum albumin levels are strongly associated with the morbidity, prognosis, and mortality rates of patients with hypoalbuminemia, which is a frequent problem during hospitalization." (PMID 33261019, 2020). "This study was designed to determine the association between hypoalbuminaemia, reversal of albumin-to-globulin ratio and morbidity outcome among confirmed LF infected patients from November 2018 to October 2019." (PMID 33312698, 2020). "All the 18 cases had hypoalbuminemia and some had serum albumin levels of ≤2.5 mg/dl as a result of protein loss because of heavy proteinuria." (PMID 32487027, 2020). "Other studies described the occurrence of hypoalbuminemia in some patients admitted with acute large cerebrovascular strokes in haemodynamically stable patients and the low albumin level was linked to mortality of those patients." (PMID 33108534, 2020). "This study was designed to determine the association between hypoalbuminaemia, reversal of albumin-to-globulin ratio and morbidity outcome among confirmed LF infected patients." (PMID 33312698, 2020). "Our results showed that low serum albumin concentration (<3.5 g/dL) (i.e., hypoalbuminemia) was also independently associated with airway invasion (OR, 4.90; 95% CI, 1.39–17.32; P = .01) among non-neurologically ill patients with dysphagia." (PMID 33157940, 2020). "Serum albumin was reported as one of the simple nutritional indicators and hypoalbuminemia was associated with a poor prognosis in chronic HF patients." (PMID 33137941, 2020). "Another previous study reported hypoalbuminemia is associated with coronary artery abnormality with odds ratio of 1.07 per 1 g/dl decrease in albumin level (p < 0.001)." (PMID 33324592, 2020). "The association between hypoalbuminemia (commonly defined as serum albumin < 3.5 g/dL) and various post-TKA complications, however, remains controversial despite numerous studies; it appears to be associated with some complications but not others." (PMID 32660593, 2020). "Serum albumin levels are strongly associated with morbidity, prognosis, and mortality in both acute and chronic disease patients, and hypoalbuminemia is a frequent problem in hospitalized patients." (PMID 33261019, 2020). "We present the case of a patient treated by OL-HDF who developed severe hypoalbuminemia resulting from massive albumin loss into dialysate." (PMID 31660886, 2019). "Loss of appetite, dialysis-induced loss of serum albumin, comorbid conditions, and enhanced protein degradation are observed with aging and suggested to be the causes of hypoalbuminemia." (PMID 30921398, 2019). "Hypoalbuminemia (albumin level below 3.5 g/dl) is considered to be associated with a higher prevalence of sepsis, and it also had a relative risk of dying of 1.52 (95% confidence interval 1.37–1.70)." (PMID 32026110, 2019). "Hypoalbuminemia (serum albumin level < 35 mg/L) was reported to be associated with deep vein thrombosis (AOR 1.69) in colon and rectal surgery." (PMID 31253199, 2019). "Among them, serum albumin was demonstrated as an indicator in cancers; hypoalbuminemia was closely associated with poor prognosis in many tumors." (PMID 31354887, 2019). "Clinicopathological changes include hyperproteinemia with hypergammaglobulinemia and hypoalbuminemia associated with a reduced albumin/globulin ratio and biochemical abnormalities (e.g. increase of azotemia and hepatic enzymes)." (PMID 30909954, 2019). "Albumin plays important physiologic functions, and hypoalbuminemia is a well-known risk factor for coronary artery disease, acute myocardial infarction, heart failure, stroke, and sepsis." (PMID 31565439, 2019).
Hypoalbuminemia (continued). "In many previous studies, low preoperative serum albumin (hypoalbuminemia) was also reported as a risk factor of postoperative morbidity and mortality." (PMID 31488117, 2019). "Vascular permeability increases during sepsis, leading to the transcapillary loss of albumin and acceleration to hypoalbuminemia." (PMID 30729384, 2019). "Patients with normal albumin levels at baseline had a relatively favourable outcome, whereas moderate or severe hypoalbuminemia was associated with two-fold higher mortality." (PMID 31095609, 2019). "A large amount of albumin (ALB) loss in the urine leads to hypoalbuminaemia and decreases plasma colloid osmotic pressure; thus, liquid can enter into the interstitial space from the vascular lumen, causing oedema formation." (PMID 30727992, 2019). "In conclusion, our data suggest that hypoalbuminemia (albumin < 3.5 g/dL) is an independent risk factor for delayed perineal wound healing." (PMID 31864365, 2019). "Gastrointestinal ulceration can lead to bleeding and albumin loss, then cause anaemia and hypoalbuminemia." (PMID 31878983, 2019). "Hypoalbuminemia was common after CA, and the serum albumin level at admission was associated with poor neurological outcomes at 6 months after CA in patients treated with TTM." (PMID 31565439, 2019). "In line with this, I recently elucidated how the loss of albumin in urine and resultant hypoalbuminemia (low levels of albumin in blood) contribute to iodine deficiency and that F− acts to induce increased urinary excretion of albumin and hypoalbuminemia." (PMID 31010095, 2019). "This suggests that hypoalbuminemia is a risk factor for death and the therapeutic target serum albumin level differs depending on age." (PMID 30921398, 2019). "Many studies have shown that hypoalbuminemia is a good predictor of morbidity and mortality, a 10-year cohort study has indicated a high risk of mortality in HD patients with serum albumin levels below 3.8g/dl." (PMID 31448023, 2019). "This was higher than anticipated in reference to previous studies (<10%) In a previous study, we documented a strong association between hypoalbuminemia and incident hypoglycemia, and the present patient population had very low albumin levels." (PMID 31398808, 2019). "Nephrotic syndrome excreting a large amount of albumin in urine causes hypoalbuminemia, which also suggests that albumin recycling following reabsorption plays a role to maintain serum levels of albumin." (PMID 30401801, 2018). "Several studies have shown that serum hypoalbuminemia can be an independent risk factor for decreased microperfusion and pressure ulcers because albumin helps maintain oncotic pressure and vascular refilling." (PMID 30158969, 2018). "Hypoalbuminaemia with low plasma albumin levels is commonly found in critically ill patients due to a decrease in synthesis by the liver, an increase in albumin degradation, and/or a loss due to capillary leakage during a period of inflammation and infection." (PMID 30643812, 2018). "This rather suggests that the kidney in these animals works properly and tries to counterbalance hypoalbuminemia by reducing renal albumin loss." (PMID 29868589, 2018). "The molecular weight of AT is lower than the molecular weight of albumin; therefore, decreases in its plasma levels caused by proteinuria are usually proportional to hypoalbuminemia." (PMID 30080915, 2018). "Mortality was inversely associated with pre-surgery albumin levels, and patients with hypoalbuminemia had a relative risk of dying of 1.52 (95% Confidence Interval (CI) 1.37–1.70, p < 0.001)." (PMID 29710860, 2018). "On the other hand, hypoalbuminemia is common in seriously ill patients, and serum albumin level has been associated with increased mortality in acutely ill patients in previous reports." (PMID 30297655, 2018).
Hypoalbuminemia (continued). "For patients suffering from hypoalbuminemia, hyperbilirubinemia or other illnesses causing an impaired transport capacity, the removal of the albumin-blocking compounds is of high importance." (PMID 29364955, 2018). "Hypoalbuminemia cannot be explained by loss of albumin through the kidney, as our data showed that albuminuria decreased in NEAA-based diet fed animals." (PMID 29868589, 2018). "The associations of preoperative low pre-albumin level and hypoalbuminemia with clinical and pathologic variables were assessed." (PMID 27906675, 2017). "Preoperative hypoalbuminemia (defined as albumin level <3.5 g/dl) is associated with compromised immunity and impaired tissue healing, which affects surgical site infections and anastomotic leakage as well as remote infections, such as pneumonia." (PMID 28570652, 2017). "Resectable HCC patients with pre-operative hypoalbuminemia are therefore at higher risk of post-operative complications, and albumin is often supplemented prophylactically prior to surgery." (PMID 29190884, 2017). "Hypoalbuminemia (deficient serum albumin) was reported in three studies with the proportion ranging from 0 to 26%." (PMID 28476156, 2017). "When hypoalbuminemia was defined by serum albumin levels of <3.5 g/dL, it remained significantly associated with the development of coronary aneurysms (11/16 vs 25/153, P < 0.001) in this study." (PMID 28587647, 2017). "Due to its systemic effects, altered albumin levels have not only been implicated in liver diseases, but hypoalbuminemia has also been identified as a risk factor for coronary artery disease and mortality in chronic kidney disease." (PMID 29113384, 2017). "In patients with advanced solid tumors, a third pathway can be activated in association with hypoalbuminemia (decreased serum albumin level)." (PMID 26988975, 2016). "This study provides new information on the temporal development of albumin kinetics during major abdominal surgery associated with hypoalbuminemia and an increase in capillary leakage." (PMID 27846908, 2016). "Hypoalbuminemia defined as serum albumin lower than 3.0 g/dL had higher risk of unfavourable outcome (38.6% vs. 16.3%, P = .020)." (PMID 27899066, 2016). "Hypoalbuminemia (albumin <3.8 g/dl) is prevalent in clinical states associated with chronic inflammation and severe oxidative stress (OS), such as in patients on hemodialysis therapy (HD)." (PMID 27453993, 2016). "The same patient presented hypoalbuminaemia (serum albumin = 1.9 g/dL) associated with peripheral oedema and pleural effusion, which resolved after anti-malarial treatment." (PMID 27230739, 2016). "Whatever the main mechanistic cause, the effects of inflammation on serum albumin levels have important consequences beyond sepsis progression; hypoalbuminemia is associated with higher mortality among patients with severe sepsis and septic shock." (PMID 26908009, 2016). "Patients with worse GI symptoms had lower serum albumin concentrations and higher risk of hypoalbuminemia in univariate regression (pathway 2)." (PMID 26651991, 2015). "A decrease in albumin synthesis, albumin loss or hemodilution can be the cause of SA 20′s hypoalbuminemia." (PMID 25880447, 2015). "The aim of this study was to investigate the risk factors of hypoalbuminemia and effects of different albumin levels on the prognosis of surgical septic patients." (PMID 26557421, 2015). "In unadjusted analyses, patients with lower eGFR had lower serum albumin levels and higher risk of hypoalbuminemia." (PMID 26651991, 2015). "Serum albumin of <3.5 g/dl and body weight loss were both significant risk factors (p < 0.001), but hypoalbuminemia was more predictive of postoperative morbidity." (PMID 26345703, 2015). "But after adding GI symptom score, CRP and 24-hour urine albumin excretion into the fully adjusted model, the association between lower eGFR and lower serum albumin/higher risk of hypoalbuminemia was basically abolished." (PMID 26651991, 2015).
Hypoalbuminemia (continued). "After adding GI symptom score or CRP into the regression analysis, neither factor attenuated the association between lower eGFR and lower albumin or hypoalbuminemia (pathway 5)." (PMID 26651991, 2015). "Now that hypoalbuminemia was significantly associated with the prognosis of sepsis, researchers were trying to infuse human albumin solutions to improve the outcomes of septic patients." (PMID 26557421, 2015). "Hypoalbuminaemia occurs as a result of loss of albumin or insufficient albumin synthesis—often as a result of inflammation or hepatic insufficiency." (PMID 26140209, 2015). "Hypoalbuminaemia in 76.7% of haemodialysis patients studied is a cause of concern thus monitoring of haemodialysis patients albumin is necessary since its decreased levels has been associated with increased morbidity and mortality." (PMID 26491522, 2015). "Weight loss and severe hypoalbuminemia were very important features since more than 90% of patients had severe weight loss and about 80% had an albumin level lower than 2 g/dL." (PMID 25492259, 2014). "PAN-induced nephrotic syndrome causes hypoalbuminemia with increased plasma T-Chol and TG, and the albumin overload caused hyperalbuminemia with increased plasma-free fatty acids." (PMID 25165480, 2014). "Findings from the Atherosclerosis Risk in Community Study revealed that serum albumin levels were inversely correlated with the risk of decline of renal function, suggesting a unique role for hypoalbuminemia as an antecedent pathway for CKD." (PMID 23607513, 2013). "Serum ferritin is measured routinely in most U.S dialysis units to guide intravenous iron therapy, and is a surrogate for inflammation that associates with short term mortality and hypoalbuminemia; it appeared to correlate with albumin <3.8 g/dl in our study." (PMID 24499139, 2013). "Since inflammation and hypoalbuminemia are two main diagnostic indices for cachexia, TB mice was subjected to serum albumin analysis." (PMID 23349693, 2013). "This study was performed to identify risk factors for hypoalbuminemia (<3.8 g/dL) and the particular temporal relationship and strength of association between protein intake (nPCR) and serum albumin when confounding variables are taken into account." (PMID 24499139, 2013). "Hypoalbuminemia in patients with renal failure is caused by a combination of reduced synthesis and increased degradation of albumin." (PMID 23016957, 2012). "In particular, preoperative hypoalbuminemia (serum albumin ≤ 3.5 g/dL) was associated strongly with medical complications and mortality, while postoperative hypoalbuminemia (serum albumin ≤ 2.7 g/dL) with surgical complications." (PMID 23285146, 2012). "All of the NHPs in this study had significant hypoalbuminemia that was possibly caused by a combination of decreased hepatic production of albumin and albumin loss through hemorrhage and/or vascular leakage." (PMID 23202456, 2012). "The important renoprotective role of serum albumin was underscored by a recent meta-analysis showing hypoalbuminemia to be a potent independent risk factor both for AKI and for death following the development of AKI." (PMID 21029460, 2010). "Hypoalbuminemia was associated with anemia (56 vs 47; p = 0.05), fatigue (58 vs 46; p = 0.01), and appetite loss (57.1 vs 46.7; p = 0.004) compared with normal albumin." (PMID 20170547, 2010). "Albumin is a major determinant of tHcy levels, being hypoalbuminemia associated with low tHcy levels." (PMID 21188242, 2010). "Akiyama has emphasized the importance of hypoalbuminemia as a risk factor, while Patil and colleagues reported a positive correlation between anastomotic leakage and an albumin level less than 30 g/L." (PMID 19881165, 2009). "Mechanistically, albumin deficiency has been associated with decreased collagen synthesis, a prolonged inflammatory phase, and delayed epithelial proliferation, which can explain the effect of hypoalbuminemia on adverse wound outcomes." (PMID 39886055, 2025).
Hypoalbuminemia (continued). "We found that even modest hypoalbuminemia was independently associated with this outcome, suggesting that albumin may serve as a useful risk stratification marker to support surgical decision-making and optimize preoperative patient management." (PMID 41228270, 2025). "A low albumin concentration has been directly linked to vitamin D deficiency, and dogs with hypoalbuminemia, such as those with PLE, might be at an increased risk of deficiency depending on the severity of their condition." (PMID 41180246, 2025). "Albumin levels may be another point of interest, as early evidence suggests that hypoalbuminemia impacts trough levels, with lower albumin levels associated with lower vedolizumab trough levels and mucosal healing." (PMID 41036260, 2025). "The glucose-albumin ratio, which integrates metabolic stress (elevated blood glucose) and nutritional depletion (hypoalbuminemia), provides a novel and valuable tool for assessing PU risk in this vulnerable population, as both factors significantly impair tissue healing capacity." (PMID 41001126, 2025). "Albumin, at the cut-off value of <4.0 g/dL, with AUC 0.73, sensitivity 70%, and specificity 74% corresponds with the result from other authors, where hypoalbuminemia, defined by an albumin level less than 3.5 g/dL, was significantly associated with worse recovery outcomes (AUC 0.72)." (PMID 41567673, 2025). "Moreover, albumin is the major binding protein for most vasoactive drugs (e.g., epinephrine, norepinephrine), and hypoalbuminemia also causes a decrease in protein binding and accelerated metabolic clearance of these drugs." (PMID 40771209, 2025). "Moreover, studies on hypoalbuminemia and thrombosis have shown that low serum albumin independently increases the risk of venous thromboembolism, likely due to impaired hepatic synthesis of anticoagulant proteins and altered endothelial function." (PMID 40688947, 2025). "Therefore, the plasma albumin level is closely related to the respiratory function of patients, which is consistent with the results of this study: Hypoalbuminemia is an independent risk factor for weaning failure." (PMID 40225039, 2025). "Hypoalbuminemia, or low levels of ALB (often defined as < 3.5–4.0 g/dL or ≤ 3.5 mmol/L), is a well-established risk factor for increased morbidity and mortality and has also been associated with mortality of sepsis; it is modifiable by ALB infusion." (PMID 40438354, 2025). "For Patient A (who developed VTE), high-risk features such as hypoalbuminemia (Albumin = 1.9), extreme obesity (BMI = 36.6), and advanced age (Age = 75) collectively elevated the predicted value [f(x) = 2.0] above the baseline E[f(x)] = 1.16, strongly indicating a poor outcome." (PMID 41573392, 2025). "Albumin levels serve as a surrogate for nutritional status, and preoperative correction of hypoalbuminemia may be critical for mitigating AL risk." (PMID 40002606, 2025). "Interestingly, while hypoalbuminemia is traditionally linked to chronic inflammation, we found higher albumin (ALB) levels to be associated with increased OSA risk (IVW OR = 1.11)." (PMID 40218080, 2025). "To better understand which clinical elements of preeclampsia are associated with hypoalbuminemia, we performed secondary analyses exploring the relationship between serum albumin and individual features such as proteinuria, renal and hepatic dysfunctions, and fetal complications." (PMID 40648529, 2025). "We hypothesized that albumin infusion may be associated with clinically unfavorable outcomes to patients with sepsis with hypoalbuminemia." (PMID 40649163, 2025). "Several studies have also shown that lower albumin levels are associated with higher rates of post-stroke hemorrhage, potentially due to increased vascular permeability and inflammation in patients with hypoalbuminemia." (PMID 40697574, 2025).